ARPC1B (actin related protein 2/3 complex subunit 1B)
Diseases named in the same sentence as ARPC1B in open-access papers (continued):
Sharing a sentence is not in itself a finding about the gene and the disease.
tumor (continued). "Corroborating these in vitro results, xenograft models demonstrated that ARPC1B depletion markedly decreased tumor growth, reinforcing its importance in tumor development." (PMID 41050079, 2025). "Validation through multiple Immunohistochemistry (mIHC) confirms the prominence of ARL4C, ARPC1B, and TERF2IP in tumor tissue, and their expression were negatively associated with CD8 T cell presence." (PMID 38419085, 2024). "The results showed that ARPC1B was significantly differentially expressed depending on the patient’s gender, different cancer stages, different tumor grades, nodal metastasis status, and histological subtypes of KIRC." (PMID 37795220, 2023). "Single-sample Gene Set Enrichment Analysis (ssGSEA), CIBERSORT, and TISCH2 analysis were used to examine the relationship between ARPC1B expression and tumor immune infiltration in KIRC." (PMID 37795220, 2023). "Based on transcription data from The Cancer Genome Atlas (TCGA), we identified four tumour-specific antigens for vaccine production: ARPC1B, ELF3, VSTM2L, and IL27RA." (PMID 37779866, 2023). "As an activator and substrate of Aurora kinase A (AURKA), ARPC1B knockout inhibits tumor migration and invasion by downregulating AURKA." (PMID 37795220, 2023). "Previously, it was shown that ARPC1B played an important role in macrophage-tumor intertwining, whereas our results demonstrated that ARPC1B was critical for the activation of intrinsic key pathways of GSCs, which is an important complement to ARPC1B for PMT." (PMID 36380368, 2022). "Tumor sphere formation assays and limiting dilution assays were applied to assess the implications of ARPC1B in tumorigenesis." (PMID 36380368, 2022). "Amongst genes we identified with copy number gain is ARPC1B which isexpressed in spontaneously transformed tumorigenic mouse ovarian surface epithelialcell lines and is positively correlated with tumor load in a mouse model of ovariancancer." (PMID 21423607, 2011). "Additionally, reactivation of the Wnt/β-catenin pathway partly reversed the inhibitory effects of ARPC1B depletion on tumor growth and invasiveness." (PMID 41050079, 2025). "Representative images confirmed smaller tumor sizes upon ARPC1B silencing." (PMID 41050079, 2025). "Furthermore, quantitative scoring revealed notably increased ARPC1B protein levels within tumor tissues (mean ± SD: 5.3 ± 2.3) relative to the paired adjacent normal samples (4.1 ± 1.6; 95% CI: 0.3442–2.096; p < 0.01)." (PMID 41050079, 2025). "ARPC1B may affect the development and progression of the tumor by regulating tumor-infiltrating cells, MDSCs and Tregs, and play an important role in the immune escape of KIRC." (PMID 37795220, 2023). "Mice xenografts were conducted to measure the effects of ARPC1B on tumor development in vivo." (PMID 37304283, 2023). "Compared to scramble control, ARPC1B interference markedly ameliorated the average tumor volume." (PMID 37304283, 2023). "However, compared to vector, the overexpression of ARPC1B significantly increased the average tumor volume." (PMID 37304283, 2023). "Additionally, overexpression of ARPC1B promoted tumor progression and resistance to radiotherapy in GSC 8-11 xenograft mice." (PMID 36380368, 2022). "However, ARPC1B was diffusely expressed in most tumor tissues." (PMID 37795220, 2023). "Therefore, we detected the mRNA and protein level of Arpc1b and EVL and concluded that ERβ might affect tumor development through the mTOR–Arpc1b/EVL signaling pathway." (PMID 33553141, 2020). "ARPC1B emerges as an essential oncogenic factor in ccRCC by stimulating EMT and activating the Wnt/β-catenin pathway, ultimately enhancing tumor aggressiveness and metastatic potential." (PMID 41050079, 2025). "Conversely, elevated ARPC1B expression strongly upregulated EMT markers, affirming ARPC1B’s crucial role in facilitating tumor cell invasiveness." (PMID 41050079, 2025).
tumor (continued). "Although the tumor burdens were similar in the three groups on Day 7, orthotopic xenografting of GSC 267 with ARPC1B knockdown exhibited a suppression of tumor proliferation." (PMID 36380368, 2022). "Thus, ARPC1B, ELF3, VSTM2L, and IL27RA were identified as potential tumour antigens for mRNA vaccine production." (PMID 37779866, 2023). "As a potential GBM antigen, targeting ARPC1B in GBM may be of great significance to promote T-cell activation and the tumor-killing function of TIICs." (PMID 34527020, 2021). "However, there is no report on the role of ARPC1B in tumor progression and tumor immunology in KIRC." (PMID 37795220, 2023). "ARPC1B, but not ARPC1A, was overexpressed in a majority of tumours." (PMID 30971746, 2019).
cancer (14 papers, 2007 to 2025). A tumor composed of atypical neoplastic, often pleomorphic cells that invade other tissues. "The ARPC1B protein has also been implicated in lamellipodia sheet membrane formation at the edge of motile cells, which relates directly to cancer cell migration and metastasis in osseous and soft tissue." (PMID 35163398, 2022). "Subsequently, we used TCGA‐PAAD transcriptome data to reveal the relationship between ARPC1B and cancer‐related biological functions and other cancer hallmarks." (PMID 40903212, 2025). "While existing research has highlighted the oncogenic role of ARPC1B in cancer progression, our findings offer new insights into its specific facet in gemcitabine resistance." (PMID 40903212, 2025). "Both analyses showed that Arp2/3 complex components’ mRNA levels are notably increased in BRCA, with ARPC1A and ARPC1B upregulated across most cancer types." (PMID 39867911, 2024). "Previous studies have shown that ARPC1B is involved in the development of various cancers, such as oral squamous cell carcinoma, hepatocellular carcinoma, and prostate cancer." (PMID 37795220, 2023). "ARPC1B was previously reported in the malignant progression of various cancer types." (PMID 40903212, 2025). "The oncogene role of ARPC1B has been observed in other cancers as well." (PMID 37304283, 2023). "Our findings implicate the role of ARPC1B in PCa invasion and metastasis in association with ERG and further support its prognostic value as a biomarker in association with ERG and PTEN in identifying aggressive phenotypes of PCa cancer." (PMID 35163398, 2022). "Despite this, the role and functions of ARPC1B in cancer are not fully understood." (PMID 35163398, 2022). "We verified by immunohistochemistry that carcinoma cells express the ARPC1B protein." (PMID 30971746, 2019). "Multiple actin-related proteins including ARPC1B, ARPC5, ACTL6A, and CFL1, which are markers for aggressive cancers, were part of the upregulated network nodes." (PMID 33317623, 2020). "Moreover, ARPC1A, ARPC1B, and ARPC5 demonstrated significant copy number amplification in most cancer types." (PMID 39867911, 2024). "In conclusion, ARPC1B and HK3 were considered the possible TAAs of GBM, and mRNA cancer vaccine therapy may be more beneficial for patients in IS2." (PMID 34527020, 2021).
infection (6 papers, 2016 to 2025). The state of being infected such as from the introduction of a foreign agent such as serum, vaccine, antigenic substance or organism. "Since Arpc1B mutations are associated with an increased propensity to develop infections, our findings open up a new therapeutic avenue, involving Arp2/3 complex augmentation, for infectious diseases." (PMID 39349750, 2024). "Three of our patients with ARPC1B mutation had developed problems with recurrent infection." (PMID 31379835, 2019). "Importantly, wt infection led to a decrease in Arpc1B levels in A-498, irrespective of the MoI used (Fig. EV3E), indicating that a reduction in Arpc1B levels is a bonafide outcome of Cg-EC interaction." (PMID 39349750, 2024).
bacterial infections (2 papers, 2021). "Our results emphasize the importance of ARPC1B for neutrophil migration, thereby explaining the severe susceptibly of these rare patients to bacterial infections, while neutrophil killing mechanisms have been found to be intact." (PMID 34135903, 2021).
ARPC1B also shares sentences with these, for which no sentence is quoted: asthma (2 papers); colitis (2); genetic disorders (2); leukocytoclastic vasculitis (2); antibody deficiency (1); autoimmune disease (1); autoimmune thyroid disease (1); autosomal recessive disease (1); bladder cancer (1); bleeding disorders (1); bronchiolitis (1); chronic granulomatous disease (1); Clear Cell Renal Cell Carcinoma (1); Congenital thrombocytopenia (1); COVID-19 (1); cutaneous vasculitis (1); dermatitis (1); enteropathy (1); Failure to thrive (1); gastrointestinal disease (1); graft versus host disease (1); Granuloma (1); hepatocellular carcinoma (1); Lymphatic Metastasis (1); mammary carcinomas (1); melanoma (1); microcephaly (1); Primary microcephaly (1); respiratory infections (1); skin infection (1).
A further 5 diseases each share a sentence with ARPC1B in 1 paper.